MYO7A (myosin VIIA)
Diseases named in the same sentence as MYO7A in open-access papers (continued):
Sharing a sentence is not in itself a finding about the gene and the disease.
infection (10 papers, 2012 to 2023). The state of being infected such as from the introduction of a foreign agent such as serum, vaccine, antigenic substance or organism. "Packaging full-length MYO7A cDNA into AAVs produced vectors with heterogeneous, fragmented genomes (fAAVs) that were able to reconstitute full-length MYO7A cDNA post-infection." (PMID 38137568, 2023). "We noticed that only a small portion of GFP+ cells turned out to be MYO7A+ HCLCs in both the sensory epithelial region and the limbus region after the infection of Ad-Atoh1 (16.00 ± 2.18% for the sensory epithelium, 12.57 ± 3.29% for the spiral limbus region)." (PMID 35082601, 2021). "Hair cell infection efficiency was assessed by quantifying the percentage of hair cells (identified by anti-Myo7a antibody) with green fluorescent protein (GFP) expression." (PMID 30683875, 2019). "Two days after infection, utricle explants were fixed and stained with antibodies for Myo7a and Sox2." (PMID 31033441, 2019). "However, two proteins smaller than the full length MYO7A (<130 KDa) are detected in vitro following infection with either the single 5′-or 3′-half of both dual AAV approaches." (PMID 24150896, 2014). "We also found VEZT and MYO7A in S. rosetta and Dictyostelium where they may serve to internalize bacteria for feeding or other non-infection purposes." (PMID 25395670, 2014). "The appearance of a small number of BrdU-positive/myosin-VIIA-positive cells after culturing in differentiation medium suggests that at least some supporting cells that reenter the cell cycle after Ad.MT58A infection retain otic identity and competency for differentiating into hair-cell-like cells." (PMID 23119091, 2012). "In our experimental set-up we confirmed the expression of MYOSIN VIIA protein and MYOSIN VIIA, POU4F3 and ESPIN mRNAs after 12 days of infection." (PMID 29979748, 2018). "Ten days after transduction with Ad-Atoh1-tdTomato virus, more than 80% of the infected cells expressed Myo7a, while cells infected with Ad-tdTomato virus remained Myo7a negative ten days after infection." (PMID 31033441, 2019). "Furthermore, preliminary experiments indicated that expression of these markers requires an even shorter time span, since high levels of MYOSIN VIIA protein expression are already observed at 7 days post-infection (data not shown)." (PMID 29979748, 2018). "Since we observed a small number of GFP-expressing hair cells after infection with Ad.GFP, we cannot rule out that the BrdU-positive/myosin VIIA-positive cells were preexisting hair cells that reentered the cell cycle after being transduced with Ad.MT58A." (PMID 23119091, 2012).
retinopathy (5 papers, 2010 to 2025). "Identifying these MYO7A variants bridges genetic research with clinical diagnostics, potentially offering more precise and personalized treatment strategies for retinal disorders." (PMID 40852359, 2025). "Among these pieQTLs, 27 are associated with retinopathies, including 3 that interact with their own eGene promoter (MYO7A, MERTK and PRPH2 genes)." (PMID 36207300, 2022). "We investigated the molecular determinant of a mild form of retinopathy in association with a subtle splicing modulation of MYO7A mRNA." (PMID 21031134, 2010). "Following these results, the same study hypothesized that MYO7A retinopathy causes photoreceptor loss as the primary event and that the inner segments of the RPE are subsequently affected during disease progression." (PMID 37762059, 2023).
genetic disorders (4 papers, 2021 to 2025). "The findings of this research also broaden our knowledge about the MYO7A variant spectrum in DFNB2 and will assist in the provision of genetic counseling for genetic disorders related to the MYO7A gene." (PMID 36164746, 2022). "USH1B is a genetic disorder caused by mutations in the unconventional Myosin VIIa protein (1–2,215 residues)." (PMID 33889793, 2021).
MYO7A also shares sentences with these, for which no sentence is quoted: Usher syndrome type 1B (35 papers); Hearing impairment (10); cancer (3); Leber congenital amaurosis (3); tumor (3); achromatopsia (2); CHARGE syndrome (2); ciliopathy (2); cystoid macular edema (2); Intellectual disability (2); Nystagmus (2); Wolfram syndrome (2); Adult onset (1); Aicardi-Goutières syndrome (1); albinism (1); amblyopia (1); amyloidosis (1); autosomal dominant nonsyndromic deafness-11 (1); communication disorder (1); cone-rod dystrophy (1); congenital myopathy (1); Crouzon syndrome (1); developmental delay (1); DiGeorge syndrome (1); dominant optic atrophy (1); DOORS syndrome (1); endolymphatic hydrops (1); epilepsy (1); gastric cancer (1); glaucoma (1).
A further 39 diseases each share a sentence with MYO7A in 1 paper.